MCL1 (MCL1 apoptosis regulator, BCL2 family member)
Diseases named in the same sentence as MCL1 in open-access papers (continued):
Sharing a sentence is not in itself a finding about the gene and the disease.
ovarian carcinoma (continued). "miR-193a induced the inhibition of DNA synthesis and apoptosis by targeting genes including ARHGAP19, CCND1, ERBB4, KRAS, MCL1, indicating a tumor suppressive role of this miRNA in epithelial ovarian cancer cells." (PMID 23588298, 2013). "Citrate, which reduces the expression of Mcl-1, dramatically increases cell death in chemoresistant human ovarian carcinoma cell lines exposed to interfering RNA targeting Bcl-xL or ABT-737." (PMID 24103422, 2013). "More recently, Bcl-xL and Mcl-1 were reported to be able to cooperate to protect ovarian carcinoma cells against oncogenic stress or chemotherapy-induced apoptosis." (PMID 22590594, 2012). "A switch in the alternative splicing of Mcl-1 has so far been shown to occur in breast and ovarian cancer, with there being an increase in the anti-apoptotic Mcl-1L isoform in cancer tissues." (PMID 23284704, 2012). "MSLN-induced Mcl-1 upregulation has been reported in taxol resistant ovarian cancer cells indicating its importance in MSLN induced protection from various apoptotic stimuli." (PMID 21880146, 2011). "Indeed, we initially demonstrated that simultaneous inhibition of the expression of Bcl‐xL and Mcl‐1 anti‐apoptotic proteins using siRNA induced massive cell death in ovarian cancer cell lines." (PMID 40483575, 2025). "Furthermore, overexpression of CCN1 can inhibit carboplatin-induced apoptosis by decreasing Bax expression and increasing Bcl-xL, Mcl-1, and Bcl-2 levels in ovarian cancer cells." (PMID 40234387, 2025). "This study aimed to evaluate whether belinostat, an FDA‐approved pan‐HDAC inhibitor, could increase Bim, Puma, and/or Noxa expression and induce ovarian cancer cell death, either alone or in combination with strategies targeting Bcl‐xL or Mcl‐1." (PMID 40483575, 2025). "This was evident based on the relatively high basal level of phosphorylated AKT in the untreated TOV21G cells, which is consistent with our other findings regarding these specific ovarian cancer cells expressing high amount of anti-apoptotic proteins (Mcl-1, XIAP, and Bcl-xL)." (PMID 39334906, 2024). "illustrated that miR-153-3p modulates ovarian carcinoma progression by regulating MCL1 expression." (PMID 37642951, 2023). "Alternatively, the more efficient DUB USP17L2 controls MCL1 turnover in ovarian cancer cells." (PMID 36551253, 2022). "However, in several other cancer types, the CASP8/MCL-1 mRNA ratio did significantly correlate with sensitivity to MEDI3039: ovarian cancer, small-cell lung cancer, neuroblastoma, DLBCL, bladder and skin cancers." (PMID 35086954, 2022). "Interestingly, USP13 was recently shown to deubiquitinate and stabilise the pro-survival protein Mcl-1 in lung and ovarian cancers." (PMID 33627786, 2021). "Therefore, DUB3 suppression or PaTrin-2 treatment significantly induces apoptosis of ovarian cancer cells by downregulating MCL1." (PMID 34454495, 2021). "If this result is confirmed in additional studies, it is possible that the constitutive presence of BAK/MCL1 complexes could be evaluated as a possible pre-selection criterion for ovarian cancers more likely to respond to paclitaxel." (PMID 34385422, 2021). "LINC00152 expedites cell proliferation by binding with miR‐125b to release MCL‐1 in ovarian cancer." (PMID 32918541, 2020). "Moreover, the progression-free survival was poorer among MCL1-positive patients than among MCL1-negative patients with ovarian cancer." (PMID 31467488, 2019). "In addition, COL11A1 interferes with anti-cancer drug-induced apoptosis in ovarian cancer cells by upregulating TWIST1-mediated Mcl-1 expression." (PMID 30975980, 2019). "In our hands, CAI potently inhibited Mcl-1 expression in ovarian carcinoma cells." (PMID 30338034, 2018). "In this line, we previously demonstrated that calcium signaling modulation targeted Mcl-1 translation and could be used to sensitize ovarian carcinoma to anti-Bcl-xL strategies." (PMID 30338034, 2018).
ovarian carcinoma (continued). "First, USP13 promoted MCL1 protein stability in multiple lung and ovarian cancer cell models." (PMID 29335437, 2018). "Thus, despite context-dependent effects on Akt activation, these results suggest that CAI down-regulates Mcl-1 translation through mTORC1 inhibition in ovarian carcinoma cells." (PMID 30338034, 2018). "Moreover, MCL‐1 was overexpressed in ovarian cancer and positively correlated with LINC00152 levels." (PMID 30030896, 2018). "The fact that the correlation between USP13 and MCL1 expression was restricted to the protein level prompted us to hypothesize that USP13 could regulate MCL1 as a deubiquitinase enzyme in lung and ovarian cancer." (PMID 29335437, 2018). "We hypothesize that CAI, via its action on SOCE and Mcl-1, could extend the therapeutic arsenal for ovarian cancer treatment if combined pertinently." (PMID 30338034, 2018). "Notably, gene expression of USP13 and MCL1 correlated with the genomic amplification status, indicative of their functional importance in driving lung and ovarian cancer." (PMID 29335437, 2018). "Furthermore, PUMA-induced decrease of Bcl-xL and Mcl-1 in ovarian cancer cells were partially rescued by SP600125." (PMID 28423586, 2017). "Interestingly, ovarian cancers with relatively high Bcl-xL levels are less responsive to taxane-based therapy, and ovarian cancer cell lines with higher Bcl-xL/Mcl-1 ratios showed higher Bliss sum values when treated with Navitoclax and taxol." (PMID 27512141, 2016). "Based on the CHI3L1 expression in ovarian cancer tissue, appropriate candidates can be selected to receive combinations of paclitaxel-platinum chemotherapy and other novel anti-apoptotic agents, especially Mcl-1." (PMID 26452028, 2015). "Here, we tested if calcium signaling pathway inhibition could have an impact on Mcl-1 expression in chemoresistant ovarian carcinoma cells and we evaluated the impact of its combination with anti-Bcl-xL strategies." (PMID 25627260, 2015). "Our results indicate that CHI3L1 could up-regulate the expression of Mcl-1 in favor of anti-apoptotic pathways to hamper the apoptosis induced by chemotherapeutic drugs in ovarian cancer cells." (PMID 26452028, 2015). "Furthermore, serous EOC ascites was found to activate PI3K/Akt and ERK1/2 pathways and stimulate the expression of Mcl-1 in ovarian cancer cells." (PMID 26122176, 2015). "Moreover, calcium pathway has already been described to regulate Mcl-1 in other types of cancer and this study suggests that Mcl-1 is also regulated by calcium signaling in ovarian carcinoma cells." (PMID 25627260, 2015). "This is followed by our in vivo-based investigation revealing for the first time the effects of minocycline to reduce both plasma and tumoral IL-6 expression along with down-regulation of tumoral p-STAT3, p-ERK1/2 and MCL-1 in an experimental model of ovarian cancer in mice." (PMID 23593315, 2013). "Since belinostat used at cytostatic concentration increased the expression of Bim and Puma while partially repressing that of Bcl‐xL, we hypothesized that combining it with strategies inhibiting residual Bcl‐xL or Mcl‐1 proteins might be effective in inducing apoptosis in ovarian cancer cells." (PMID 40483575, 2025). "The objective of this study was to evaluate whether belinostat could be an interesting pharmacological tool to increase the expression of Bim, Puma, and/or Noxa, and to induce apoptosis in ovarian cancers, either alone or in combination with strategies targeting Bcl‐xL or Mcl‐1." (PMID 40483575, 2025). "It has been demonstrated, on ovarian cancer cell lines, that the activation of the Ob-R determined an inhibition of apoptosis and an increased cell proliferation via the upregulation of the expression of cyclin D1 and myeloid cell leukemia-1 (Mcl-1), which are apoptosis regulators." (PMID 34440886, 2021).
ovarian carcinoma (continued). "In another example, miR-142-5p targeted several antiapoptotic genes, including baculoviral IAP repeat-containing 3 (BIRC3), B-cell lymphoma-2 (BCL2), BCL2-like 2 (BCL2L2), and myeloid cell leukemia sequence 1 (MCL1), and could improve cisplatin-mediated anticancer function in ovarian cancer." (PMID 31861383, 2019). "However, whatever are the MR22388 direct targets, we focused our attention on possible indirect effects of MR22388 on Bcl-2 family members since we previously demonstrated that anti-apoptotic proteins Bcl-xL and Mcl-1 cooperate to protect ovarian carcinoma cells against apoptosis." (PMID 23735052, 2013). "Based upon this pilot study, we examined the relationship between phospho-ERK1/2 and Mcl-1 expression in a tissue microarray (TMA) of HGSOC provided by the Pan-canadian platform for the development of biomarker-driven subtype specific management of ovarian carcinoma (COEUR study)." (PMID 23158473, 2012). "It is well known that Mcl-1 pre-mRNA undergoes alternative splicing events to produce two functionally distinct proteins, Mcl-1S (pro-apoptotic) and Mcl-lL (anti-apoptotic); the latter isoform is predominant in different cancers including breast and ovarian cancer cells." (PMID 23284704, 2012). "In ovarian cancer (SK-OV-3 and SK-OV-3/DDP) cells, apigenin reduces myeloid cell leukemia-1 (Mcl-1) mRNA and protein levels, a member of the anti-apoptotic Bcl-2 family, thereby reversing cisplatin resistance." (PMID 40490812, 2025). "In ovarian cancer, MCL1 is stabilized by MGMT-activated DUB3, leading to resistance to platinum/paclitaxel-based chemotherapy in ovarian cancer cells." (PMID 38254819, 2024). "Researchers have demonstrated that oncogenes PIK3CA, MCL1, MYCN, DHFR, and eIF-5A2 were over-amplified via eccDNA in primary ovarian cancers, ovarian cancer cell line UACC-1598 and cervical cancer cell line HeLa, respectively." (PMID 37233789, 2024). "Here, the authors found that TRIM47 knockdown reduced STAT3 phosphorylation at Tyr705 in both cultured and xenografted ovarian cancer cells, followed by reduced expression of the STAT3 target genes MCL-1, MMP2, and c-MYC." (PMID 36288633, 2022). "In lung and ovarian cancer cells, USP13 deubiquitinates and stabilizes MCL1, a key member of the anti-apoptotic BCL-2 family." (PMID 35898882, 2022). "Overall, compared to the acute lymphoid leukemia cell line Jurkat in our previous studies, ovarian cancer cells have about 2–8 times more BCLXL and 8–50 times more MCL1, but much less BCL2." (PMID 34385422, 2021). "In ovarian cancer cells, DUB3 interacts with MCL1 to deubiquitinate and stabilize MCL1 through its 40th lysine at the N-terminus." (PMID 34454495, 2021). "SRT2183 inhibited the growth of ovarian cancer cells, increased the accumulation of BAX, cleaved-caspase 3 and cleaved-PARP, and decreased the level of anti-apoptotic Bcl-2 and Mcl-1." (PMID 33223507, 2020). "In paclitaxel-resistant ovarian cancer cells, blocking of STAT3 activity suppresses STAT3 downstream antiapoptotic regulatory genes BCL2L1, MCL1, and BIRC5, which increases paclitaxel sensitivity in paclitaxel-resistant ovarian cancer cells in vitro." (PMID 31861720, 2019). "In summary, based on ceRNA theory, the combined research on miR‐125b and MCL‐1, and taking LINC00152 as a new study point, we provide new insight into the molecular mechanism of reversing cell proliferation in ovarian cancer." (PMID 30030896, 2018). "Recently, we showed that calcium chelation by BAPTA-AM and calmodulin inhibition by W7 led to a decrease in Mcl-1 via down-regulation of the mTORC1/4E-BP1 pathway and sensitized ovarian cancer cells to anti-Bcl-xL strategies." (PMID 30338034, 2018).
ovarian carcinoma (continued). "Here, we provided several lines of evidence to support that MCL1 was a deubiquitination target of USP13 in lung and ovarian cancer." (PMID 29335437, 2018). "In conclusion, we show that CAI has an anti-proliferative effect on ovarian cell lines and that it inhibits Mcl-1 expression through SOCE/mTORC1 inhibition, which leads to a strong sensitization of ovarian carcinoma to anti-Bcl-xL strategies." (PMID 30338034, 2018). "BCL-2, BCL-XL, MCL-1 and BAX are determinants of apoptosis in response to chemotherapeutic agents, and are variably expressed in ovarian cancers." (PMID 28399108, 2017). "As Mcl-1 represents a crucial hurdle to the success of chemotherapy, these results could open to new area of investigation using calcium modulators to directly or indirectly target Mcl-1 and thus efficiently sensitize ovarian carcinoma cells to anti-Bcl-xL strategies." (PMID 25627260, 2015). "To analyse if Mcl-1 decrease upon BAPTA-AM treatment involves proteasomal degradation, we incubated ovarian carcinoma cells with bortezomib, a proteasome inhibitor, for 1 h and then treated cells with BAPTA-AM for 6 h." (PMID 25627260, 2015). "The dual PI3K/mTOR inhibitor NVP-BEZ235 that decreases Mcl-1 expression, synergized with ABT-737 in inducing apoptosis of ovarian carcinoma cells, provided that Bim expression was induced." (PMID 26405162, 2015). "We therefore studied the effect of different calcium signals inhibitors in ovarian carcinoma cell lines SKOV3 and IGROV1-R10 and analysed their effects on proliferation and Mcl-1 expression." (PMID 25627260, 2015). "Ovarian carcinomas often overexpress anti-apoptotic proteins such as BCL-XL and MCL1 and thereby shift the balance toward survival, which provides them with a major advantage in protecting themselves from chemotherapeutic agents." (PMID 24523919, 2014). "We sought to identify miRNAs that can efficiently induce apoptosis in ovarian cancer cells by overcoming BCL-XL and MCL1 anti-apoptotic activity, using combined computational and experimental approaches." (PMID 25299770, 2014). "Beyond inhibiting Bcl‐xL and Mcl‐1, increasing the expression levels of these pro‐apoptotic members, especially the BH3‐only proteins Bim, Puma, and Noxa, has proven to be an interesting strategy for triggering apoptosis in ovarian cancer cells." (PMID 40483575, 2025). "Finally, our data show that colorectal and ovarian cancer cells can be sensitized to Taxol by genetic inhibition of TRIP12 and this effect is largely dependent on FBW7 and MCL-1 proteins." (PMID 36672454, 2023). "Because DUB3 has been demonstrated to drive chemoresistance in colorectal cancer and ovarian cancer via stabilizing NRF2 and MCL1, we explored whether DUB3 affects the response of HCC cells to the commonly used chemotherapeutic drugs for HCC treatment." (PMID 35383144, 2022). "Like cervical cancer, ovarian cancers are squamous cell carcinomas; therefore, we hypothesised that USP13 might also regulate Mcl-1 in cervical cancer cells." (PMID 33627786, 2021). "Finally, various anti‐apoptosis proteins of the Bcl‐2 family such as pBcl‐2, Mcl‐1, Bcl‐XL, and XIAP10 should also be explored in order to fully improve cisplatin sensitivity in ovarian cancer treatment." (PMID 30019389, 2018). "USP13 and MCL1 were readily detectable in most ovarian cancer specimens, and analysis of consecutive tissue sections discovered a significantly positive correlation between USP13 and MCL1 expression (Spearman’s rank correlation coefficient R = 0.60, P = 2.61 × 10−4)." (PMID 29335437, 2018). "As a whole, this study suggests that CAI sensitizes to anti-Bcl-xL strategies via its action on Mcl-1 translation and that modulation of SOCE could extend the therapeutic arsenal for treatment of ovarian carcinoma." (PMID 30338034, 2018). "DCA alone significantly increased the level of Mcl-1 protein (but not Bcl-2 and Bcl-xL proteins) in ovarian cancer cells, which was markedly attenuated by Met." (PMID 27449090, 2016).
ovarian carcinoma (continued). "Our data showed that induction of apoptosis and cell cycle G1 arrest are key components of the anti-tumorigenic effects of NT1014 in ovarian cancer cells, as evidenced by induced expression of annexin V, p27, and p21 as well as reduction of BCL, Mcl-1, cyclin D1, and CDK expression." (PMID 27655410, 2016). "In summary, we demonstrated that LA induced massive apoptotic cell death through inhibition of the two anti-apoptotic proteins Mcl-1 and Bcl-xL, and induction of the pro-apoptotic BH3-only protein Bim in two human ovarian cancer cells (one sensitive and one resistant to cisplatin)." (PMID 26063499, 2015). "In this study, using in silico prediction algorithms and functional studies, we attempted to uncover miRNA(s) that could induce apoptosis in ovarian cancer cells by targeting BCL-XL and MCL1 and identify key signalling pathways involved." (PMID 25299770, 2014). "In these two ovarian carcinoma cell lines, western blot analysis showed that exposure of SKOV3 cells to citrate at 20 mM led to a decrease in the expression of the anti-apoptotic protein Mcl-1, as from 6 H compared to control cells." (PMID 24103422, 2013). "Mcl-1 inhibits apoptosis by heterodimerizing with pro-apoptotic Bcl-2 members via its BH3 domain and is upregulated in several cancers, including lung, breast, colon, ovarian carcinoma, and gastric cancer, mediating resistance to apoptosis induced by conventional chemotherapy and targeted therapy." (PMID 38928234, 2024). "However, studies have also shown that USP13 may act as an oncogene by promoting Mcl-1 stability in cervical cancer, and USP13 also drives the progression of ovarian cancer by promoting cancer metabolism." (PMID 36564767, 2022). "Indeed, we found that USP9X knockdown did not convincingly alter MCL1 protein levels in multiple lung and ovarian cancer cell lines." (PMID 29335437, 2018). "Notably, it has also been reported that BAG3 positively regulates the expression level of MCL-1 through the down-regulation of miR-29b and that the combined expression of BAG3 and MCL-1 confers resistance to chemotherapy-induced apoptosis in ovarian cancers." (PMID 30273361, 2018). "However, it does not bind to Mcl-1 and Bfl-1 that prevents it to induce cell death in tumor models that overexpress these anti-apoptotic proteins, such as ovarian cancer." (PMID 25627260, 2015). "LINC00152 mediates cell proliferation, thereby affecting MCL-1 expression and mitochondrial apoptosis pathways via MCL-1, and acts as a competitive endogenous RNA (ceRNA) of miR-125b, which may represent a novel molecular mechanism for reversing cell proliferation in ovarian cancer." (PMID 39337410, 2024). "By analyzing the expression levels of MCL1 and the other DUBs in nine ovarian cancer cell lines, we observed that only DUB3, and not USP9X or USP13, showed a significant positive correlation with MCL1, further supporting our hypothesis that DUB3 is the crucial DUB that modulates MCL1 stability." (PMID 32699213, 2020). "As we previously showed that Mcl-1 is a target for calcium signaling, we investigated whether CAI could modulate the expression of Mcl-1, with a special attention to the molecular mechanism involved and whether it could sensitize platinum-refractory ovarian cancer cells to anti-Bcl-xL strategies." (PMID 30338034, 2018). "Moreover, the anti-tumoral effect of this combination could explain the mild efficacy of CAI when it was used as a single agent in clinical trials, as the sole inhibition of Mcl-1 is not sufficient to induce apoptosis in ovarian cancer." (PMID 30338034, 2018). "In lung and ovarian cancers, where USP13 also regulates Mcl-1 stability, USP13 does not contribute to the cell proliferation of unstressed cells." (PMID 33627786, 2021). "It was found that FBW7 prompts ubiquitination and degradation of MCL1, while lack of FBW7 elevates MCL1 expression leading to resistance to antitubulin therapy in ovarian cancer." (PMID 33658012, 2021).